IL9 (interleukin 9)
Diseases named in the same sentence as IL9 in open-access papers (continued):
Sharing a sentence is not in itself a finding about the gene and the disease.
atherosclerosis (14 papers, 2013 to 2024). A disease characterized by the build-up of fatty material and calcium deposition in the arterial wall resulting in partial or complete occlusion of the arterial lumen. "CT-1 deficiency in advanced atherosclerosis mediated regulation of paracrine factors, such as interleukin (IL)-3, IL-6, IL-9, IL-15, IL-27, CXCL5, MCP-3, MIP-1α and MIP-1β." (PMID 32238841, 2020). "In contrast, IL-9 was functionally linked to aggravated atherosclerosis in Apoe−/− mice by the induction of vascular cell adhesion molecule 1 expression." (PMID 31641089, 2019). "More research is needed to fully elucidate the role of Th9 cells and IL-9 in the pathogenesis of atherosclerosis." (PMID 39161593, 2024). "Clinically, IL-9 plasma levels are higher in patients with atherosclerosis and with an acute coronary syndrome, while the count of TH9 cells was unchanged in another study." (PMID 33669769, 2021). "Accordingly, the downregulation of CASC11 in the plasma of atherosclerosis patients was found to promote VSMC proliferation and the expression of IL-9, which contributes to atherosclerosis." (PMID 31998442, 2020). "Circulating Th9/IL-9 levels were increased in patients with acute coronary syndrome (ACS) and in atherosclerotic mice, whereas recombinant mouse IL-9 treatment aggravated the development of atherosclerosis in high-fat diet-fed ApoE-/- mice." (PMID 32148441, 2020). "The identified genes were enriched by pathways such as atherosclerosis, IL-6, IL-9, IL-8, growth hormone, and JAK/STAT signalling pathways." (PMID 31205673, 2019). "The top pathways included growth hormone signaling, IL-9 signaling, atherosclerosis, and IL-6 signaling." (PMID 27955697, 2016). "This suggests a role for the IL-9/IL-9R interaction in atherosclerosis, but the functional consequences of these findings are at present unclear." (PMID 24023645, 2013). "In murine models of atherosclerosis, IL-9 has been found to have pro-atherogenic effects." (PMID 39161593, 2024). "IL-9 administration seems to promote atherosclerosis in Apoe−/− mice, but the overall role of TH9 cells remains unknown." (PMID 33669769, 2021). "Increased IL-9 plasma levels were found in patients with ACS or atherosclerosis." (PMID 28349060, 2017). "Although IL-4 and IL-5 protect against atherosclerosis, IL-9 may promote atherosclerosis." (PMID 39684449, 2024). "We focus on the contribution of cytokine networks encompassing IL-4, IL-6, IL-9, IL-17A, IL-33 but also IFN-γ and TNF-α to vascular dysfunction in atherosclerosis." (PMID 32194407, 2020). "Thus, IL-9 may be the novel contributing factor in atherosclerosis." (PMID 32148441, 2020). "Although interleukin (IL)-9 has been related to inflammation, there are at present no data on its role in atherosclerosis." (PMID 24023645, 2013).
lymphoma (14 papers, 2010 to 2025). A malignant (clonal) proliferation of B- lymphocytes or T- lymphocytes which involves the lymph nodes, bone marrow and/or extranodal sites. "Conversely, IL-9 can support tumor growth in IL-9R-expressing malignancies, including lymphomas, lung cancer and pancreatic cancer." (PMID 41030439, 2025). "In lymphoma, tumor cells often secrete IL-9 to promote their own proliferation and inhibit apoptosis." (PMID 39852828, 2025). "IL-9, however, stimulates the proliferation of lymphoma cells and protects them from the effects of dexamethasone-induced apoptosis." (PMID 35211408, 2022). "In mice, a gene-transfer-induced overexpression of IL-9 promoted lymphoma generation; in humans, high levels of IL-9 are associated with a poor prognosis in HL patients." (PMID 34680190, 2021). "The dysregulated expression of IL-9 has been detected in biopsies or serum specimens of patients with some malignant lymphomas, such as HD, ALCL and NKT-cell lymphoma, which provides clinical evidence for its possible involvement in lymphomagenesis." (PMID 27364124, 2016). "In fact, IL-9 transgenic mice transplanted with NPM-ALK-transfected BM cells developed not only ALK+ lymphomas, but also various types of benign and malignant MC lesions." (PMID 21297223, 2010). "The carcinogenic activity of IL-9 in lymphomas has already been demonstrated by numerous studies." (PMID 35211408, 2022). "Using a neutralizing antibody to block the binding of IL-9 to IL-9R could significantly inhibit the tumor growth in mouse models of lymphoma." (PMID 35211408, 2022). "In addition, IL-9 could stimulate the proliferation of lymphomas and protect them from dexamethasone (DEX)-induced cell apoptosis." (PMID 35211408, 2022). "In addition, IL-9 could indirectly mediate the immunosuppressive effects on mastocytes and Treg cells in mouse models of lymphoma to inhibit tumor growth." (PMID 35211408, 2022). "This may imply that the tumorigenic effect of IL-9 also exists in other types of lymphoma." (PMID 27364124, 2016). "However, the pathogenic role of IL-9 in lymphomas derived from B-cell lineages has not been previously reported." (PMID 27364124, 2016). "In addition, deletion of IL9R may affect JAK-STAT signaling in response to IL9, which is another pathway important in normal B cells and lymphomas." (PMID 25123191, 2014). "All IL-9-transgenic mice that had received NPM–ALK-transduced hematopoietic precursor cells developed hematopoietic malignancies, including various types of lymphomas." (PMID 21297223, 2010). "Recently, EBERs were found to increase transcription or mRNA stability of IL-10, IL-9, or IGF1 in lymphoma or carcinoma cell lines." (PMID 20144199, 2010). "EBER induces IL-9 expression, suggesting that EBV may play a role for IL-9 expression in the lymphoma." (PMID 31041299, 2019). "However, the oncogenic activities of IL-9 in lymphomas derived from B-cell lineages have not been reported in detail." (PMID 27364124, 2016). "However, although secondary recipients were found to develop ALK+ lymphomas in most cases, no MC neoplasms could be detected in any of these animals independent of the presence or absence of an IL-9-background." (PMID 21297223, 2010). "IL-9/NPM-ALK+ mice with no apparent accumulations of MC (n=15) died early, some during the acute period after transplantation (marrow aplasia), others from aggressive lymphomas, suggesting that MC neoplasms developed later than lymphomas in mice." (PMID 21297223, 2010).
atopic dermatitis (13 papers, 2008 to 2025). "Nonetheless, the anti-inflammatory properties of rosiglitazone in vitro align with therapeutic benefits of PPAR-γ agonists in IL-9-associated diseases such as atopic dermatitis and psoriasis." (PMID 41030439, 2025). "In addition, a recent report indicates that IL-18 drives secretion of pathogenic cytokines from Th2 cells in atopic dermatitis, with IL-9 upregulating the IL-18R on Th2 cells." (PMID 40489556, 2025). "Interleukin (IL)-9 is present in atopic dermatitis (AD) lesions and is considered to be mainly produced by skin-homing T cells expressing the cutaneous lymphocyte-associated antigen (CLA)." (PMID 39201262, 2024). "Previous studies showed the IL-9 level elevation in several dermatological diseases, including atopic dermatitis, psoriasis vulgaris, and cutaneous T-cell lymphoma." (PMID 37398641, 2023). "In atopic dermatitis, IL-9 levels correlated with clinical severity, IgE levels, and C-C motif chemokine ligand 17 (CCL17) levels." (PMID 37398641, 2023). "They exhibit transient IL-9 production, heightened IL-13, and IL-5 secretion, a tendency to express the skin-homing receptor known as cutaneous lymphocyte-associated antigen (CLA), and are typically located in skin lesions of atopic dermatitis (AD), psoriatic, and contact dermatitis patients." (PMID 39201262, 2024). "Gene-expression of IL-9 and IL-9 receptor is significantly increased in lesional skin areas of atopic dermatitis (AD) patients as compared to normal control skin, while serum IL-9 is not different from controls." (PMID 22413008, 2012).
experimental autoimmune encephalomyelitis (13 papers, 2014 to 2025). An autoimmune demyelinating disease of the central nervous system that is produced experimentally in animals by the injection of homogenized brain or spinal cord in Freund's adjuvant. "IL-9 neutralization and IL-9 receptor deficiency led to a reduction in Th17 cells and IL–6-producing macrophages in the central nervous system, ultimately ameliorating the development of experimental autoimmune encephalomyelitis in mice." (PMID 37894114, 2023). "Through biochemical, immunohistochemical, and electrophysiological experiments, we investigated the effects of both peripheral and central administration of IL-9 on C57/BL6 female mice with experimental autoimmune encephalomyelitis (EAE), a model of MS." (PMID 38745307, 2024). "Recently, Th9 cell and its secreting cytokine IL-9 have been implicated in MS, which activates and cooperates with other CD4+T cells and CNS-resident cells in MS and experimental autoimmune encephalomyelitis (EAE), an animal model of MS." (PMID 33971906, 2021). "Recently, the chemokine IL-9 has been shown to play a major role in regulating autoimmune responses in experimental autoimmune encephalomyelitis, which is an animal model of MS." (PMID 33391265, 2020). "The murine model of experimental autoimmune encephalomyelitis was used to explore the influence of IL-9 blockage on Th17-related inflammation response, suggesting IL-9 might play the role as a Th17-mediated cytokine." (PMID 29887863, 2018). "In contrast, a study observed IL-9 neutralization followed by attenuated Th17 responses in an animal model of experimental autoimmune encephalomyelitis, implicating that IL-9 might contribute to inflammatory disease as a Th17-mediator cytokine." (PMID 29887863, 2018). "Although IL9 was previously regarded as one of the Th2 type cytokines, it was recently reported that IL9-producing CD4+T cells can induce neuroinflammation in certain conditions and that Th17 cells can produce IL9, which exacerbates experimental autoimmune encephalomyelitis." (PMID 25919001, 2014). "A published study on experimental autoimmune encephalomyelitis indicated that STAT1 and STAT3, but not STAT5, regulated IL-9 mediated IL-17 production in T cells." (PMID 29887863, 2018).
Stroke (13 papers, 2012 to 2026). Sudden impairment of blood flow to a part of the brain due to occlusion or rupture of an artery to the brain. "We observed that low stroke risk patients exhibited higher GATA-3, Foxp3, PU.1, AHR, IL-9, IL-10 and IL-22 expression levels than did patients with high stroke risk." (PMID 27115869, 2016). "In experimental stroke, expressions of IL-9 and its upstream stimulating factors has been confirmed to be increased." (PMID 35173738, 2022). "IL-5 and IL-9 are decreased in severe stroke patients acute ischemic stroke patients with poor outcome than mild stroke." (PMID 35173738, 2022). "Neutralization of IL-9 ameliorates post-stroke damage to the blood-brain barrier (BBB) via down-regulating astrocyte-derived VEGF-A, which suggested VEGFA as a novel therapeutic target of immune intervention of IS." (PMID 35419038, 2022). "In our study, we found that serum concentrations of IL-4, IL-5 and IL-9 were significantly elevated in minor stroke patients and negatively related to the NIHSS score." (PMID 31164999, 2019). "In this study, we demonstrated that patients with low stroke risk have increased mRNA expression of GATA-3, Foxp3, PU.1, AHR, IL-9, IL-22 and IL-10." (PMID 27115869, 2016). "The differentiation of helper lymphocytes into Th2 is promoted by interleukins IL-4 and IL-9, and their reduced expression may indicate an impaired humoral response in stroke patients." (PMID 40520895, 2025). "This was evidenced by a significant increase in the levels of multiple inflammatory cytokines including IP-10, KC, MCP-1, MIP-1α, MIP-1β, MIP-2, RANTES, IL-9, IL-4, and IL-12 (p70) within the infarct at eight weeks post stroke when compared to naïve brain tissue." (PMID 30417081, 2018). "Moreover, of relevance to stroke, IL-9 has been shown to protect cortical neuron from cell death by anti-apoptotic mechanisms, and further studies are clearly needed to elucidate the net effect of IL-9 levels in atherosclerotic disorders." (PMID 24023645, 2013). "The seven important predictor genes (CCR4, IFNA2, IL-9, IL-7, IL-5, CCR3, and IL-27) that overlapped both stroke outcomes had mean fold change ranging from 3.98 to 35.06." (PMID 32010048, 2019). "The intersection of the top 10 genes from the two stroke outcomes are seven genes with T2DM, these include CCR4, IFNA2, IL-9, IL-7, IL-5, CCR3, and IL-27." (PMID 32010048, 2019). "Previous reports characterized an acute immune response to ischemic stroke by profiling certain cytokines and chemokines (e.g., IL-1α and β, IL-6, IL-8, IL-9, IL-10, IL-12, IL-18, TNFα and soluble TNF-receptors p55, p75 and GRO-α) in the sera or cerebrospinal fluid of stroke patients." (PMID 31164999, 2019). "However, it must be noted that in a severe, permanent carotid artery occlusion model of stroke, simultaneous deletion of IL-13, IL-9, IL-4, and IL-5 did not worsen the neurological outcome." (PMID 36639371, 2023). "We initially screened 35 inflammatory mediators in 75 patients, and found that IL-4, IL-7, IL-9, GM-CSF and MIP-1α were significantly decreased in the severe stroke group, compared with control group (P < 0.05; data not shown)." (PMID 31164999, 2019).
liver fibrosis (12 papers, 2016 to 2024). "In a group of patients with advanced liver fibrosis, liver steatosis was linked with lower serum concentrations of IL-4, IL-5, IL-9, IL-10, IL-13 and IL-22." (PMID 39200991, 2024). "In the present study, we analyzed the association between Th9/IL-9 and liver fibrosis in patients with either LC (liver cirrhosis) or CHB (chronic hepatitis B)." (PMID 26728971, 2016). "In a subgroup of patients with advanced liver fibrosis, SLD was linked with lower serum concentrations of IL-4, IL-5, IL-9, IL-10, IL-13 and IL-22 and higher concentrations of HGH and VEGF." (PMID 39200991, 2024). "IL-9 antibodies were shown to improve hepatic fibrosis, which is consistent with studies on pulmonary fibrosis disease." (PMID 38879568, 2024). "IL-9 is also markedly elevated in liver cirrhosis patients and is crucial to the development of hepatic fibrosis." (PMID 36835428, 2023). "Another study found that IL-9 activated the Raf/MEK/ERK signaling pathway signaling model of liver fibrosis brought on by the chemical carbon tetrachloride (CCl4)." (PMID 36835428, 2023). "In a CCl4-induced mouse model of hepatic fibrosis, compared with the controls, significantly elevated Th9 cells in spleen, and high expression of IL-9 in plasma and liver were all observed." (PMID 34234100, 2021). "Recent evidence indicates that Th9 cells and its signature cytokine IL-9 play a deleterious role in increasing hepatic fibrosis." (PMID 34234100, 2021). "Considering that IL-9 promoted liver fibrosis via Raf/MEK/ERK signaling pathway, Raf/MEK/ERK pathway was also examined." (PMID 34234100, 2021). "In liver cirrhosis patients, IL-9 is also significantly increased and has been proven to play an important role in hepatic fibrosis progression." (PMID 32676074, 2020). "IL-9 has further been reported to activate Raf/MEK/ERK signaling pathway in a commonly used carbon tetrachloride (CCl4)-induced liver fibrosis mouse model." (PMID 32676074, 2020). "Consistent with studies in lung fibrotic diseases, IL-9 antibody inactivates hepatic stellate cells (HSCs) and ameliorates liver fibrosis." (PMID 32676074, 2020). "Out study showed that treatment with anti-IL-9Ab and anti-IL-17Ab exerted similar effects on suppressing plasma secretion and liver expression of TGF-β1, IL-6, TNF-α, IL-4 and IL-9 in mice with liver fibrosis." (PMID 26728971, 2016). "Plasma concentrations of IL-9 and IL-17A were both remarkably higher in mice with liver fibrosis than in controls." (PMID 26728971, 2016). "We aimed to investigate the role of Th9/interleukin-9 (IL-9) in the pathogenesis of hepatic fibrosis." (PMID 26728971, 2016). "Splenic Th9 and Th17 cells, plasma concentrations and liver expression of IL-9 and IL-17A were significantly elevated in mice with hepatic fibrosis compared with controls." (PMID 26728971, 2016). "The percentages of Th9/IL-9 cells significantly elevated in both patients and mice with liver fibrosis, suggesting that the microenvironment induced by liver fibrosis favors Th9 proliferation and IL-9 secretion." (PMID 26728971, 2016). "To investigate the role of IL-9 in modulating hepatic fibrosis in vivo, we treated the mouse model of hepatic fibrosis with IL-9-neutralizing antibodies (anti-IL-9Ab) by intraperitoneal (IP) injection." (PMID 26728971, 2016). "To better understand the role of IL-9 in regulating inflammatory response, we measured levels of inflammatory cytokines in plasma and liver tissues of mice with liver fibrosis." (PMID 26728971, 2016). "We further delineated differences between IL-9 and IL-17 and their roles that played in liver fibrosis by using levels of IL-21 as an indicator." (PMID 26728971, 2016). "Similarly, IL-9 levels are markedly increased among liver cirrhosis patients and have been demonstrated to contribute significantly to the advancement of liver fibrosis." (PMID 38879568, 2024). "In a mouse model of liver fibrosis, IL-9 was found to activate the Raf/MEK/ERK signaling pathway." (PMID 38879568, 2024).